CD44 (CD44 molecule (IN blood group))
Diseases named in the same sentence as CD44 in open-access papers (continued):
Sharing a sentence is not in itself a finding about the gene and the disease.
colon carcinoma (continued). "The side population of colon cancer cell line SW480 exhibits high ABCG2 mRNA and transporter expression, accompanied by high CD44 mRNA and protein levels, regarded as a key marker of solid tumour CSCs." (PMID 37445716, 2023). "Our flow cytometry experiments revealed that a high dose of EUG (500 μM) effectively decreases the population of CD44+, CD133+, and LgR5+ cells in a metastatic colon cancer cell line." (PMID 36831488, 2023). "FXR-KO mice exhibited elevated colon cancer markers (β-catenin, LGR5, CD44, CD34, and cyclin D1) under LPS, underscoring the pivotal role of FXR in inhibiting the development of colon tumorigenesis." (PMID 38069256, 2023). "Makkar found that the combination of HA with CD44 and TLR4 can promote the development of colon cancer, and PEP1 can block the combination of HA with receptors, and inhibit the growth of colon cancer." (PMID 37020597, 2023). "In colon cancer, enhanced SOX2 expression reversed the downregulation of CD133 and CD44 and the upregulation of E-cadherin 58, and inhibition of SOX2 decreased Snail expression, leading to a decrease in the invasive migratory capacity of cells." (PMID 37213675, 2023). "In colon cancer, tumor cells with high SOX2 expression have an enhanced sphere-forming ability and are accompanied by elevated expression of the CSC markers CD44 and CD2447." (PMID 37213675, 2023). "In vitro targeting studies were conducted using human colon cancer cells (SW480 and Caco2 cell lines) and lung normal cell (WI38 cell line), which were selected for their varying expression of CD44 and folate receptors." (PMID 37685852, 2023). "In human colon cancer SW480 cells, reduced level of HNRNPLL enhanced expression of the CD44 isoforms containing exons v3-v10 and cell invasion activity." (PMID 38106992, 2023). "To further verify the effect of TP5 on colon cancer stem cells, we used flow cytometry to detect the expression of cancer stem cell markers CD24, CD44 and CD133, which are surface markers that can be specifically expressed by colon cancer stem cells." (PMID 35242031, 2022). "Last, we correlated the CD44 and NUMB isoforms expression in patient-derived colon cancers with functional signatures obtained by averaging the scaled expression levels for each of the hallmark sets." (PMID 36346211, 2022). "CD44 and NUMB alternative splicing (AS) isoforms have opposite functions in quasi-mesenchymal and epithelial colon cancer cells and their capacity to metastasize the liver." (PMID 36346211, 2022). "Colon cancer stem cells can express specific surface markers such as CD24, CD44 and CD133, which are highly resistant to radiotherapy and chemotherapy." (PMID 35242031, 2022). "Furthermore, the phosphorylation of the CD44 intracellular domain can directly trigger intracellular signaling, particularly tyrosine kinase, including the Akt protein, for supporting growth, motility and invasion in many types of cancer, including breast, prostate, and colon cancers." (PMID 33780455, 2021). "Western blots confirmed clear protein bands of CD44 expression on human HT29 and SNU-C5 human colon cancer cells and THP-1 human monocytic cells." (PMID 33594192, 2021). "In particular, in colon cancer, CCSCs have been identified in established colon cancer cell lines or in primary tumors through their expression of CD133, CD44, CD166, Lgr5, EpCAM, ALDH1 and β-catenin alone or through combinations of these markers." (PMID 33819194, 2021). "(A) Flow cytometric analysis of the colon cancer cell lines HCT116 and SW480 with antibodies directed against CD44 and EpCAM." (PMID 34036938, 2021).
colon carcinoma (continued). "Further evaluating the colon cancer stem cell (CSC) markers, we found that both CD44 and CD166 expression were reduced in the DSS-induced colon cancer samples of mice treated with the same drugs, particularly the combination of niclosamide and metformin." (PMID 34298652, 2021). "In the present study, to investigate the relationship between PRDX2 expression and CD133+CD44+ CCSCs, immunohistochemical (IHC) staining was conducted to determine the expression of PRDX2 in CD133(+)/CD44(+) and CD133(-)/CD44(-) colon cancer patients." (PMID 33819194, 2021). "Currently, colon cancer stem cell (CCSC) populations have been isolated and identified by several markers, such as CD133, CD44, CD166, Lgr5, EpCAM, ALDH1 and β-catenin." (PMID 33819194, 2021). "Protein expression of CSC-markers prominin-1 and CD44 antigen was significantly higher for BKZ-2 and BKZ-3 in comparison to well-established colon carcinoma cell lines." (PMID 32927768, 2020). "Coexpression of CD133 and CD44 was detected in a majority of cells in the HCT116 and HT29 cell lines, which is in line with previous evidence that colon cancer cell lines contain the TIC cell-like subset." (PMID 32729895, 2020). "Positive regulation of CD44 expression in ERK-dependent manner was detected in response to both, SphK1 overexpression and exogenous S1P stimulus in oxaliplatin-sensitive colon cancer cells." (PMID 32456134, 2020). "Our findings are in line with studies in colon cancer indicating a positive relationship between MSI proteins and CD44." (PMID 32245259, 2020). "Among colon cancer SW480 cells, the extra domain A of fibronectin drove tumorigenesis by maintaining the properties of CD133 + /CD44 + subgroup." (PMID 33303029, 2020). "In the YUMC-C1 and YUMC-C2 drug-resistant and metastatic colon cancer cells, respectively, metastatic genes (CDH2, KRAS, CDC42, MCPH1, SRGAP) and markers of stemness (BRACA1 and 2, CD44, KRT5, WNT4, CD29, SAL4) were markedly enhanced." (PMID 33050525, 2020). "At present, the main colon cancer stem cell markers include CD133, CD44, CD90, ALDH1A1, EpCAM, SOX2, SOX9, LGR5, etc., and they are usually used to identify and isolate CSCs." (PMID 33680915, 2020). "Combined with the findings from CD44 SBTA, these data suggest DBTA can potentially distinguish between distinct functional P-selectin ligands expressed in situ on colon carcinoma tissue." (PMID 31186472, 2019). "CD44+CD133+ high-expressing and other populations of human DLD-1 colon cancer cells were separately isolated through fluorescence-activated cell sorting." (PMID 31619711, 2019). "It is reported that suppression of sp1 expression reduced the growth of colon cancer stem cells (CCSC) and induced apoptosis in vitro and in nude mouse xenografts, and the proportion of CCSC markers, CD44+/CD166+, was decreased following sp1 knock-down." (PMID 31614732, 2019). "For example, fluorouracil-resistant colon cancer cells express higher level of CD133 and CD44 proteins." (PMID 30935014, 2019). "In fact, the tumor sphere formation ability was decreased, and the levels of a panel of established CSC markers, including CD133, CD44, Sox2, Oct4, Nanog, and ALDH1A1, were decreased in colon cancer cells treated with GM‐Exo subjected to S100A9 knockdown." (PMID 31559140, 2019). "Consistently higher expression of CD133, SOX2, NANOG, OCT4, CD44 and Lgr5 in ALDH+ cells, which was the representative markers of CSC, validated the truth of stemness of ALDH+ colon cancer cells." (PMID 30962766, 2019). "For example, in colon cancer, cell surface markers such as CD133, CD44, ALDH and ATP-binding cassette sub-family B member 5 (ABCB5) were reported to be a identification of CSCs." (PMID 30962766, 2019). "We next investigated the effects produced by perturbation of O-GlcNAc levels on the expression of stem cell markers CD44 and CD133 by pharmacological inhibition of OGT or OGA in colon cancer cells." (PMID 31139149, 2019).
colon carcinoma (continued). "Silencing EDA in colon cancer SW480 cells reduced spheroid formation and reduced double positive CD133+/CD44+ cells." (PMID 29747682, 2018). "This differential behavior of M5-T1 compared with F4-T2 and F5-T1 was also observed for FIBB, CD44, and VWA5A, in agreement with the fact that both CD44 and VWA5A were interesting markers for detection of the early stages of colon cancer in the plasma." (PMID 29662647, 2018). "We also found increased expression of stem cell markers, including OCT4, Lin28, KLF, Bmi-1, CD44 and SOX2, in colon cancer cells upon treatment with BM-MSCs-derived exosomes." (PMID 30220706, 2018). "Previous studies have shown that the colon cancer stem cells isolated from HCT116 cells express high levels of PROM1 (CD133), CD44, EPCAM, SOX2, c-MYC, and NANOG." (PMID 29507661, 2018). "Currently, highly tumorigenic and self-renewing colorectal CSC populations in human colon cancers have been successfully enriched and identified with a series of markers, including CD133, CD44, and CD1077,23." (PMID 30275459, 2018). "Serial chemotherapy can promote the enrichment of CSCs and tumor repopulation via COX‐2/PGE2 signaling in bladder cancer 10, and PGE2 can increase CD44+ and CD133+ CSCs subpopulation‐mediated EP4 signaling in colon cancer." (PMID 29683262, 2018). "First, it was shown that TGF-β1, a well-known inducer of EMT and of colon cancer liver metastases, stimulates tumor sphere formation; TGF-β inhibitors reduced CD44 expression in tumor spheres." (PMID 29652830, 2018). "Control alginate cultures of HCT116 and HCT116R colon cancer cells showed basal expression of CSC markers (ALDH1, CD44 and CD133)." (PMID 30002278, 2018). "Primary colon cancer cells were maintained in serum-free medium to form spheres and CD133+/CD166+/CD44+ spheroid cells were selected using FACS technique." (PMID 29110645, 2017). "In this study, CD44 and CD133 were shown to have significant potential as two biomarkers for colon cancer stem cells." (PMID 26840024, 2016). "In Sahlberg's experiment, three colon cancer cell lines HT-29, HCT-116, and DLD-1 expressed different amounts of CD133, CD44, and other markers." (PMID 26840024, 2016). "In this study, we identify that a colon cancer cell line, HCT-116 yield a high percentage of CD44+/CD133+ cells and look further into their relevance to tumor growth property in colon cancer." (PMID 26840024, 2016). "To delineate CD44 and CD133 expression in colon cancer cells, we used flow cytometry to measure the level of expression of these surface molecules in various colon cancer cell lines." (PMID 26840024, 2016). "We demonstrated enrichment of CD133, CD44, and CD24-positive cell populations and increased sphere-forming capacity following cumulative exposure to NNK in colon cancer cells." (PMID 26992205, 2016). "In regards to T84 colon cancer cells, TS1 and TS2 showed a higher enrichment in cells with a CD44+/CD326+ phenotype, even when their expression was studied together or separate." (PMID 26752044, 2016). "In this study, CD133 and CD44 expressed cells were found to be highest in the HCT-116 cells, a metastatic colon cancer cell line." (PMID 26840024, 2016). "In colon cancer, the CD44+/EpCAM+ or CD133+ subpopulation initiates tumorigenesis and differentiates into colon cancer cells." (PMID 26474460, 2015). "While colon cancer cells express both CD133 and CD44, the presence of these markers alone is probably insufficient to identify CSCs." (PMID 25941936, 2015). "In colon cancers, certain putative cancer stem cell markers, including CD133, CD44 and EpCAM, have been used to identify colon CSCs." (PMID 25789015, 2015). "In colon cancer, the HA-CD44v6 interaction and recruitment of ERBB2 also induces the transcription of COX2 initiated downstream of CD44 through PI3K-Akt and β-catenin." (PMID 25999946, 2015). "CD44 is one of the genes activated by β-catenin, and CD133 positive colon cancer cells have a higher β-catenin expression level." (PMID 24760019, 2014).
colon carcinoma (continued). "In the present study, we have investigated the differences in the expression patterns of CD133, CD24, CD44 and EGFR in three colon cancer cell-lines; HT-29, HCT116 and DLD-1." (PMID 24760019, 2014). "We found that CD44 and CD24 were present abundantly in human colon cancer tissues, and conversely, both of them were weakly detectable in human adjacent noncancerous colon tissues." (PMID 24696849, 2014). "We have further verified this interaction, with flow cytometry, western blot and mRNA expression analysis in the colon cancer cell-line DLD-1 by showing that knock-out of AKT1, AKT2 or both AKT1 and AKT2 increased the expression of CD44." (PMID 24760019, 2014). "Earlier, we reported a predominance of CSCs/CSLCs in CR colon cancer cells that show increased ability to exclude drugs, and elevated expression of CSC markers such as CD44, CD166, CD133 and ALDH." (PMID 24465408, 2014). "The extensively used method to isolate or enrich colon cancer stem cells is cell sorting based on cell surface markers, such as CD133, CD44, Musasai-1, etc." (PMID 24039918, 2013). "Currently studied CSC surface proteins in colon cancer include EpCAMhigh, CD133, CD26, CD166, and CD44, independently or in combination." (PMID 23308131, 2013). "Our data revealed correlations in the expression of surface markers CD44 and CD24 as well as CD44 and CDCP1 and strongly suggest that CD133 is a stem cell marker within our colon carcinoma panel." (PMID 22433494, 2012). "Our study characterized a large panel of colon carcinoma cell lines and their corresponding xenografts, showing significantly reduced expression of the cell surface markers CD133, CD44, CD24, CDCP1 and CXCR4 in vivo." (PMID 22433494, 2012). "By immunoprecipitating CD44 from PDGF-treated and untreated LS174T colon carcinoma cells, which express primarily CD44v, we demonstrate that PDGF enhances the adhesion of CD44v-coated beads to immobilized fibrin." (PMID 23056168, 2012). "A small subset of CD133-positive colon carcinoma cells additionally expressed CD24, CD44 or CDCP1, so that a correlation in antigen expression can be assumed." (PMID 22433494, 2012). "We characterized a panel of fourteen human colon carcinoma cell lines and their corresponding xenografts for the surface expression of potential stem cell markers CD133, CD24, CD44, CDCP1 and CXCR4." (PMID 22433494, 2012). "For example, a glycoform of CD44 known as HCELL (hematopoietic cell E−/L-selectin ligand), a major E-selectin ligand expressed by human colon cancer and hematopoietic stem cells, was found to be reactive to HECA-452 mAb by Western blot." (PMID 22970241, 2012). "This behavior is different for the colon cancer cell lines HT29 and Caco2, which were reported in CD44 and CD133 reduced after treatment with sodium butyrate." (PMID 22895640, 2012). "Overall, the data presented herein showed that CRCs have a wide range of expression for CD44 and CD133; it is unlikely the CSCs can be characterized by any single marker or the same set of markers for all colon cancer cells." (PMID 22895640, 2012). "Since the majority of cells express either CD133 or CD44 in many types of colon tumor cells, it is unlikely that a single marker of CD133 or CD44 can be used to distinguish CSCs." (PMID 22895640, 2012). "The combination of CD44 and CD133 correlated with more features of CSCs, but they cannot be generalized and applied for all colon cancer cells." (PMID 22895640, 2012). "Several E-selectin ligands have been identified on human colon cancer, prostate cancer, leukemic, and hematopoietic cells, such as CD43, PSGL-1, CD44, PCLP, and CEA." (PMID 22970241, 2012). "There are a few papers that reported CD44 as well as ALDH and CD133 are markers of colon cancer stem cells." (PMID 21694723, 2011). "The activation of CD44 isoforms also triggers resistance to chemotherapeutic agents in non-small cell lung cancer (NSCLC) and colon cancer cell lines." (PMID 21819617, 2011).
colon carcinoma (continued). "By inhibiting DLL4 with human monoclonal antibody 21M18 in colon carcinoma xenografts, the tumor growth as well as the CSC frequency, measured by the amount of ESA+CD44+CD166+ cells is decreased compared to control." (PMID 21311095, 2010). "Expression of none of the CD44 variant epitopes was found to be positively correlated with tumour progression or with colorectal tumour metastasis to the liver, results which are inconsistent with a role for CD44 variants as indicators of colonic cancer progression." (PMID 8695347, 1996). "In colon cancer cells, invasion and migration levels are positively regulated by RUNX2 and Brahma-related gene 1 (BRG1) which form a complex regulating cluster of differentiation 44 (CD44) signaling pathway." (PMID 41511334, 2025). "Also, high CD44 expression is known to be positively correlated with vimentin levels and EMT features in various cancers, including gastric and colon cancers." (PMID 40518514, 2025). "Remarkably, as few as 10 CD44(hi) cells were capable of forming tumors in 70% of mice, whereas CD44(-) colon tumor cells were non-tumorigenic." (PMID 39247186, 2024). "As for colon cancer, whether ESRP1 regulates AS of CD44 and other target genes downstream of EMT/MET activation during invasion and metastasis is yet poorly understood." (PMID 36346211, 2022). "Secondly, CD24, CD44 and CD133 are specific surface markers that can be expressed by colon cancer stem cells; ALDH1, OCT4, SOX2 and Nanog are all markers of stemness status of cancer stem cells, which are important for maintaining the nature and drug resistance of cancer stem cells." (PMID 35242031, 2022). "In the present study, we found that TP5 can directly inhibit cultured colon cancer stem cells in medium without serum, and reduce the expression of cancer stem cell markers: CD44, CD24 and CD133, and stem-cell related genes: ALDH2, SOX2, OCT4 and Nanog." (PMID 35242031, 2022). "Furthermore, CD44 and the transcription factor SP-1 was probably involved in the inhibitory effect of CBS/H2S axis on colon cancer cells." (PMID 35172821, 2022). "Gene and pathway correlation analyses of CD44 and NUMB isoforms in patient-derived colon cancers." (PMID 36346211, 2022). "Subsequently, we assessed whether the stem cell function-regulating role of PRDX2 in CD133+CD44+ CCSCs involves Wnt signaling and the EMT process which play crucial roles in colon cancer initiation, metastasis and stemness maintenance." (PMID 33819194, 2021). "We observed increased Srx and Prxs mRNA expression in CSCs sorted using CD133, CD44, and Lgr5 antibodies relative to non-CSCs in several colon cancer cell lines." (PMID 34798428, 2021). "They showed modification of MSNs with both EpCAM and CD44 aptamers could coordinately restrain proliferation and metastasis of SW620 colon cancer cells." (PMID 34641857, 2021). "However, CD44, NCAM1,SYP, and NCAPG showed higher expression levels than NCM-460 in the majority of colon cancer cell lines." (PMID 35155186, 2021). "In addition, PSVII@MCP-CaP significantly reduced the protein expressions of CD44, MMP-9 and N-cadherin in drug-resistant colon cancer tissue, while the expression of E-cadherin was increased." (PMID 34789268, 2021). "Treatment of HCT116 colon cancer cells with 70 μg/ml of C. orbiculata extract resulted in an increase in the co-precipitation of hnRNPA2B1 with BCL2L1, BCL2, MDM2, cMYC, CD44, CDK6, and cJUN mRNA." (PMID 33163396, 2020). "The suppression of CD44 expression was induced by inhibition of either SphK1 activity or by blocking S1PR2 receptor leading to down-regulation of CD44 expression levels and ERK activity in resistant colon cancer cells." (PMID 32456134, 2020). "In contrast, CD44 is thought to be extensively involved in the process of colon cancer metastasis, but it seems to not present long-term tumorigenic potential." (PMID 32729895, 2020). "In colon cancer, the well-established markers of CSCs are CD133 and/or CD44." (PMID 32423158, 2020).